VHL (von Hippel-Lindau tumor suppressor)
Diseases named in the same sentence as VHL in open-access papers (continued):
Sharing a sentence is not in itself a finding about the gene and the disease.
kidney cancer (continued). "It is well known that the occurrence of most kidney cancers is closely related to the abnormal function of the von Hippel-Lindau (VHL) gene." (PMID 35245343, 2022). "We first considered RCC, an adult kidney cancer where the cancer cell transcriptome can be definitively identified based on the tumour marker CA9, caused by the near universal disruption of the VHL gene underpinning RCC11." (PMID 36071103, 2022). "Through the in-depth study of VHL gene and the development of gene transfection technology, gene therapy for kidney cancer with VHL gene as a target has bright prospects." (PMID 35035522, 2022). "Due to the management complexity of VHL patients and lack of clear guidelines on when to initiate therapy, we sought to survey VHL kidney cancer experts across the United States to gain insight into future utilization." (PMID 36310638, 2022). "Herein, we sought to gain insight about future utilization by surveying VHL kidney cancer experts in the United States." (PMID 36310638, 2022). "Most kidney cancer patients overexpress VEGF, EGF, PDGF, TGF2a, and other growth factors due to VHL gene mutation and abnormal growth of tumor tissues resulting in HIF-related transcriptional activation." (PMID 35035522, 2022). "We next applied HP5 to the analysis of mTOR pathways, which are frequently dysregulated along with hypoxia signaling pathways in VHL-defective kidney cancer." (PMID 36097292, 2022). "In conclusion, VHL kidney cancer specialists anticipate a paradigm shift with the approval of belzutifan." (PMID 36310638, 2022). "The average growth rate of HLRCC-associated kidney cancer is estimated to be 1.06 cm per year, whereas the median growth rate of von Hippel-Lindau (VHL)-associated kidney cancer is 0.37 cm per year and that of BHD-associated kidney cancer is 0.1 cm per year." (PMID 35874919, 2022). "U.S. Food and Drug Administration (FDA) has approved 7 drugs targeting the VHL signaling pathway, but the guiding significance for overall clinical outcome and the survival of kidney cancer patients were very limited." (PMID 34606472, 2021). "Recent studies have reported multiple genes that are possibly involved in the occurrence and development of kidney cancer, such as VHL, MET and FLCN." (PMID 34606472, 2021). "Recently, variations in VHL and PBRM1 mutation rates were observed according to ancestry, with fewer mutations in African kidney cancer patients." (PMID 33668731, 2021). "Recently, several characteristic kidney cancer-related genes, including VHL, MET, FLCN, TSC1, TSC2, FH, and SDH, have been reported to affect the metabolic stress response." (PMID 33686951, 2021). "For example, pVHL-based PROTAC cannot be used to treat most kidney cancers since majority of kidney cancers lack functional VHL protein." (PMID 33142830, 2020). "Specifically, we performed western blot analysis on lysates from characterized RCC4 kidney cancer cells which lack VHL and RCC4 cells stably expressing VHL." (PMID 33370271, 2020). "HIF increases KDM5C levels and activity, and the overall level of H3K4me3 is elevated when KDM5C is suppressed in VHL-defective kidney cancer cells." (PMID 30355451, 2018). "We observed similar differences for kidney cancer cell lines with inactivated VHL as compared to cell lines with wild-type VHL." (PMID 30006568, 2018). "Our finding that a drug combination of rapamycin and AICAR resulted in an 80% decrease in tumor size compared with 38% with rapamycin or 36% with AICAR, underscores the potential utility of this drug combination for kidney cancer, including VHL−/− RCCs." (PMID 30107094, 2018).
kidney cancer (continued). "GLS was selectively amplified only in the presence of the VHL mutation (HI-HI Boolean implication), GLS amplification resulted in increased expression of GLS, and GLS was differentially overexpressed in VHL-mutant compared to VHL-wild-type kidney cancer." (PMID 28561042, 2017). "The constitutively high level of HIF activity shifts the VHL-defective kidney cancer cells metabolism from oxidative phosphorylation toward glycolysis to derive ATP without using molecular oxygen." (PMID 24260413, 2013). "Inactivating VHL alterations were found in 9/12 (75%) patients with a self-reported family history of kidney cancer; 8 case tumors had inactivating alterations, and 1 had a hypermethylated VHL promoter." (PMID 22022277, 2011). "This indicates that the EGFR is critical for the tumorigenesis of VHL-defective ccRCC cells and is a credible therapeutic target in kidney cancer." (PMID 21949687, 2011). "Prior to the discovery of the VHL gene, kidney cancer was regarded as a single disease." (PMID 41544251, 2026). "Kidney cancer was regarded as a single disease until the VHL gene was discovered." (PMID 41544251, 2026). "VHL families with null VHL alleles develop kidney cancer and hemangioblastomas without a high risk of paraganglioma." (PMID 39320914, 2024). "For instance, large deletions of VHL and C3orf10, as well as BRK1, have been associated with lower lifetime risk of kidney cancer, whereas the deletion encompassing VHL and the FANCD2 gene may be linked to an increased susceptibility to breast cancer." (PMID 39336783, 2024). "The involvement of the VHL-HIF-VEGF axis in kidney cancer development was detected in the 1990s." (PMID 37964226, 2023). "Mutational inactivation of the VHL tumor suppressor gene causes an inappropriate accumulation of the hypoxia-inducible transcription factor (HIF), which promotes tumorigenesis in the context of kidney cancer." (PMID 37445575, 2023). "VHL-null kidney cancer cell lines led to the discovery of the role of pVHL and prolyl hydroxylases in negatively regulating HIF, but overexpression of mutant pVHL, PHD2, or HIF2α remains a blunt tool that is not well-suited for differentiating different disease classes." (PMID 36040300, 2022). "VHL-null 786-O cells were resistant to apoptosis in contrast to VHL wild-type-expressing cells when treated with sorafenib, a multi-kinase inhibitor approved for the treatment of primary kidney cancer." (PMID 35760869, 2022). "The findings suggest that genes associated with kidney cancer, including VHL, MET, FH, FLCN, TSC1, TSC2, and SDH, are involved in metabolic pathways linked to oxygen and iron or nutrient sensing, thus characterizing kidney cancer as a cellular metabolic disease." (PMID 35873461, 2022). "In kidney cancer, two KIRC and one KIRP patients carried GJB2, three KIRP patients carried MET, one KIRC and two KRIP patients carried MUTYH and three KIRC patients carried VHL germline mutations." (PMID 36451132, 2022). "VHL-HIF-HRG pathway provides a new target for the treatment of kidney cancer in multiple links." (PMID 35035522, 2022). "VHL gene is a potential target for gene therapy of kidney cancer." (PMID 35035522, 2022). "The VHL-HIF-HRG pathway provides new targets for the treatment of kidney cancer in multiple links." (PMID 35035522, 2022). "Machine predictive control techniques may be utilized in diagnosis of kidney cancer based on the biostatistics of VHL-gene transfection." (PMID 35035522, 2022). "Comprehensive characterization of the regulation of gene expression by the HIF–VHL and mTOR pathways is crucial to understanding the biology of VHL-defective kidney cancer, particularly as agents targeting both these pathways are being deployed therapeutically." (PMID 36097292, 2022). "VHL and other crucial drivers of kidney cancer activate both the WNT and NOTCH pathways." (PMID 32066735, 2020).
kidney cancer (continued). "Previous studies have shown that seven known kidney cancer genes, VHL, MET, FLCN, TSC1, TSC2, FH, and SDH, are involved in pathways that respond to metabolic stress or nutrient stimulation, suggesting that kidney cancer is a disease of dysregulated cellular metabolism." (PMID 31649873, 2019). "It represents a new alternative for treatment of kidney cancer inducing cell death of VHL mutated cells by apoptosis without autophagy induction." (PMID 26018559, 2015). "Interestingly, kidney cancer has been suggested as a metabolic disease, many kidney cancer genes like VHL, MET and TSC1/2 are involved in metabolism-related pathways." (PMID 25408144, 2014). "Although the function of PHF15 is largely unknown, the closely related molecule PHF17 has been shown to have tumor suppressor activity in kidney cancer: PHF17 is normally stabilized by the VHL protein and prevents tumor growth by inducing apoptosis." (PMID 23577124, 2013). "Additionally, we treated MS147 to 786‐O cells, a kidney cancer cell line that contains a truncated, inactive VHL (and thus cannot be utilized by VHL‐recruiting PROTACs), to further demonstrate the correlation between MS147's BMI1/RING1B degradation activity and its antiproliferative effect." (PMID 36737841, 2023). "Whether or not belzutifan can change the natural history of VHL-associated kidney cancer is unclear and will require further follow-up data." (PMID 36310638, 2022). "Similarly, genes frequently mutated in human kidney cancer such as VHL were not identified in the RENCA model." (PMID 31898484, 2020). "Multiple genes linked with kidney cancer, including the VHL, MET, FLCN, fumarate hydratase, succinate dehydrogenase, TSC1, TSC2, and TFE3, were identified by genomic studies and have significantly altered the ways in which patients with kidney cancer are managed." (PMID 29254180, 2017). "In malignancies such as kidney cancer and pancreatic neuroendocrine tumors where a therapeutic role of Sunitinib has been established, the absence of the VHL gene causes accumulation of HIFs and the production of several growth factors, including VEGF and PDGF against which Sunitinib has efficacy." (PMID 27974690, 2016). "By relating circulating nutritional metabolites to proximal tubule metabolic sensitivity and VHL-HIF-dependent regulation, this review aims to bridge systemic nutritional metabolism with metabolic reprogramming characteristic of kidney cancer." (PMID 41835382, 2026). "Although we succeeded in generating VHL−/−ccRCCs in mice using somatic gene editing of VHL and other kidney cancer suppressor genes that strongly resemble human ccRCC tumors in some respects, these lesions were not HIF2 dependent." (PMID 39365820, 2024). "This suggests that VHL−/− ccRCCs can evolve toward HIF2-independence over time, perhaps aided by selection pressures imparted by kidney cancer therapies." (PMID 39365820, 2024). "Widely recognised kidney cancer targeted agents fall into two categories, TKI and mTOR inhibitors, acting through VHL/HIF/VEGF and PI3K/AKT/mTOR signalling pathways respectively." (PMID 36741716, 2022). "Previous studies have found that several genes, including VHL, PBRM1 and TSC1, played an important role in tumorigenesis of kidney cancer." (PMID 34193180, 2021). "In kidney cancer, the pro- or anti-oncogenic role of autophagy is mediated by two different forms of autophagic protein LC3, LC3B and C, which are regulated by the VHL protein." (PMID 28326269, 2015). "Inactivation of the VHL tumor suppressor protein is a common event in clear cell RCC, which is the most common form of kidney cancer." (PMID 24944633, 2014). "Among all kidney cancers, clear cell renal cell carcinoma (ccRCC) is the most common with a molecularly distinct phenotype and contain up to 91% nonfunctional VHL mutations which may leads to the constitutive expression of hypoxia inducible factors 1 and 2 alpha (HIF-α)." (PMID 22804960, 2012).
kidney cancer (continued). "CDK4 had 0 carriers with melanoma, while VHL had 1 carrier with kidney cancer, and the OR was non-significant (3.5 [0.49, 25.4], p = 0.21)." (PMID 40073867, 2025). "Although it has been well-documented that VHL triggers HIFs instability and inhibits tumor growth, its role in the kidney cancer development has not been fully elucidated until now." (PMID 37833251, 2023). "Compared with the transfected VHL gene, kidney cancer cell lines that were not transfected with the VHL gene had low expression of the VHL gene, cell growth activity was not inhibited, and cell apoptosis rate was low." (PMID 35035522, 2022). "To investiage whether the VHL-S65W signature possess clinical significance in KIRC patient prognosis, we performed a Kaplan–Meier survival analysis in several cohorts of human kidney cancer data sets." (PMID 35505422, 2022). "It is not surprising that the distribution of 3p deletion among kidney cancer entities was comparable to the frequencies of VHL deletion." (PMID 32076485, 2020). "In both a distinct type of kidney cancer not characterized by chromosome 3p LOH or VHL inactivation, and a tumor of completely different cellular origin, we observed a DNA hypermethylation phenotype strongly linked to SETD2 mutation." (PMID 26646321, 2016). "Down-regulation of HIF2α expression in VHL-/- kidney cancer cells did not inhibit cellular growth under standard cell culture condition." (PMID 24260413, 2013). "Inactivated VHL fails to degrade HIF α subunits (HIFα) in kidney cancer cells." (PMID 36542714, 2022). "Besides VHL gene, miR-21 may degrade PTEN mRNA leading to the activation of Akt and mTOR kinases which contribute to growth and migration of kidney cancer cells." (PMID 28326269, 2015).
hemangioblastoma (125 papers, 2008 to 2026). "We performed whole exome sequencing on 22 familial hemangioblastomas from 7 patients representing 5 unrelated families, and with 4 different causative VHL genotypes." (PMID 41870981, 2026). "Individuals with VHL-associated hemangioblastomas typically experience an earlier disease onset and have a less favorable prognosis due to the formation of multiple neoplasms." (PMID 40091097, 2025). "In contrast, multiple hemangioblastomas have been reported in humans, most of which are associated with mutations in the von Hippel–Lindau (VHL) gene." (PMID 41158610, 2025). "In the context of VHL-deficient hemangioblastomas, the stabilization of both HIF-1α and HIF-2α has been suggested to drive the tumor’s highly vascularized environment, thereby promoting its growth and survival." (PMID 40427061, 2025). "Sporadic hemangioblastomas in humans are frequently solitary and are reported to occur more commonly than VHL-associated cases." (PMID 41158610, 2025). "Their findings suggest that the occurrence of hemangioblastomas and other glial tumors is associated with alterations in the VHL gene." (PMID 41155273, 2025). "We conducted an immunohistochemical study to assess FSHR1-expression in VHL-associated tumors including ccRCC, CNS-hemangioblastoma, and panNET." (PMID 41024941, 2025). "FSHR-protein expression was detected in the BV endothelial cells in 100% of VHL-associated CNS-hemangioblastoma, panNET, and ccRCC cases." (PMID 41024941, 2025). "At the moment, Belzutifan, an oral HIF-2α inhibitor, is the only one approved by the FDA to treat VHL-associated renal cell carcinoma, hemangioblastomas, and pancreatic and neuroendocrine tumors." (PMID 41155273, 2025). "In this study, we show results from FSHR1 expression analysis in 71 samples of VHL-associated tumors representing ccRCC, panNET, and CNS-hemangioblastoma located in cerebellum, spinal cord, intradural/extramedullary, and brain stem." (PMID 41024941, 2025). "The patients in our case series were first diagnosed at ages 34, 19, and 21, consistent with the earlier onset of VHL associated hemangioblastomas compared with sporadic cases (mean age 29 vs. 47)." (PMID 41302074, 2025). "Regarding the difference in tumor control rates between VHL-associated and sporadic hemangioblastomas, it is noteworthy that VHL-associated lesions tend to be smaller and asymptomatic at the time of discovery and radiosurgery compared to sporadic lesions." (PMID 40091097, 2025). "Together with these previous reports, our results suggest a potential role of FGFR2 in the development and progression of VHL-mutated hemangioblastomas." (PMID 40393028, 2025). "Regarding SNC hemangioblastomas, the analysis of tissues with mutations in the expressions of VHL gene showed the JAK2 and STAT3." (PMID 39272694, 2024). "VHL-associated as well as sporadic hemangioblastomas in children and adolescents are extremely rare (incidence < 1:1,000,000)." (PMID 38647646, 2024). "Hemangioblastomas, highly vascular tumors that can arise in the central nervous system, retina, and other locations, are a hallmark of VHL." (PMID 39272694, 2024). "VHL-associated hemangioblastomas share similar molecular and morphological features with embryonic blood and vascular precursor cells." (PMID 37174017, 2023). "When a single lesion is shown, even if total removal of VHL-associated hemangioblastomas is surgically feasible, patients can develop multiple lesions in different areas from the primary region." (PMID 36611440, 2023). "During our research on the pathogenesis of VHL disease, we made three important observations regarding VHL-associated hemangioblastomas." (PMID 37174017, 2023). "The present work shows the importance of personalized medicine in, the case of a VHL patient bearing a second inherited mutation, which we propose as the trigger for the growth of his CNS hemangioblastomas." (PMID 37843608, 2023).